CD40 (CD40 molecule)
Description:
Receptor for TNFSF5/CD40LG. Transduces TRAF6- and MAP3K8-mediated signals that activate ERK in macrophages and B cells, leading to induction of immunoglobulin secretion (By similarity).
Synonyms: TNFRSF5; p50; Bp50; CDW40
Tractability: Antibody: a drug acting on it is in phase 2 or 3 trials; its Gene Ontology location is reachable by antibodies, with high confidence; UniProt places it where antibodies can reach, with medium confidence; UniProt predicts a signal peptide or a membrane-spanning region. PROTAC: its protein half-life has been measured; a small molecule that binds it is known. Other modalities: a drug acting on it is in phase 2 or 3 trials.
Target class: Membrane receptor
Gene: Protein-coding gene on chromosome 20 (46,118,249 to 46,129,872, forward strand). Ensembl gene ENSG00000101017.
Subcellular location: Cell membrane (Isoform I); Secreted (Isoform II)
Subcellular location (Human Protein Atlas): Vesicles; Plasma membrane; Predicted to be secreted
Pathways (Reactome):
Immune System: Immunoregulatory interactions between a Lymphoid and a non-Lymphoid cell; TNF receptor superfamily (TNFSF) members mediating non-canonical NF-kB pathway; TNFR2 non-canonical NF-kB pathway
Gene Ontology:
Molecular function: enzyme binding; protein binding; signaling receptor activity; ubiquitin protein ligase binding
Biological process: CD40 signaling pathway; cell surface receptor signaling pathway via JAK-STAT; cellular response to mechanical stimulus; intracellular calcium ion homeostasis; positive regulation of angiogenesis; positive regulation of blood vessel endothelial cell migration; positive regulation of canonical NF-kappaB signal transduction; positive regulation of endothelial cell apoptotic process; positive regulation of interleukin-4-mediated signaling pathway; positive regulation of MAPK cascade; positive regulation of protein kinase C signaling; positive regulation of transcription by RNA polymerase II; B cell activation; B cell proliferation; immune response-regulating cell surface receptor signaling pathway; inflammatory response; platelet activation; protein-containing complex assembly; B cell mediated immunity; defense response; positive regulation of developmental process; positive regulation of multicellular organismal process; regulation of gene expression; regulation of immune response
Cellular component: cell surface; extracellular exosome; plasma membrane; CD40 receptor complex; external side of plasma membrane; extracellular region
Genetic constraint (gnomAD): Loss-of-function variants: 19 observed, 41.19 expected, observed/expected ratio (o/e) 0.46, 90% interval 0.32 to 0.68. The upper end of that interval is the gene's LOEUF score, 0.68, which puts it in group 2 of 6, group 1 being the genes least tolerant of losing a copy. Missense variants: 256 observed, 361.74 expected, observed/expected ratio (o/e) 0.71, 90% interval 0.64 to 0.79. Synonymous variants: 130 observed, 135.99 expected, observed/expected ratio (o/e) 0.96, 90% interval 0.83 to 1.11.
Gene-disease validity (ClinGen):
ClinGen rates the evidence that CD40 causes each of these diseases.
hyper-IgM syndrome type 3 (autosomal recessive): Definitive. A form of Hyper IgM syndrome characterized by mutations of the CD40 gene.
Homologues: Orthologues: chimpanzee CD40 (99% identical), macaque CD40 (94% identical), pig CD40 (73% identical), guinea pig CD40 (68% identical), dog CD40 (64% identical), mouse Cd40 (62% identical), rat Cd40 (60% identical), tropical clawed frog cd40 (35% identical). Paralogues in human: LTBR (29% identical), TNFRSF11A (28% identical), TNFRSF21 (27% identical), TNFRSF1B (26% identical), TNFRSF11B (22% identical), NGFR (21% identical), TNFRSF8 (21% identical), TNFRSF14 (21% identical), TNFRSF1A (21% identical), TNFRSF9 (19% identical), RELT (18% identical), TNFRSF4 (18% identical), and 9 more.
Diseases named in the same sentence as CD40 in open-access papers:
CD40 is named in the same sentence as 472 diseases in open-access papers, as found by Europe PMC text mining. Sharing a sentence is not in itself a finding about the gene and the disease. The quoted sentences say what the papers report.
autoimmune disease (121 papers, 2006 to 2026). A disorder resulting from loss of function or tissue destruction of an organ or multiple organs, arising from humoral or cellular immune responses of the individual to their own tissue constituents. "The CD40 molecule is known to play a central role in the co-stimulation of T and B cells and has also been linked to the pathogenesis of autoimmune diseases." (PMID 40843700, 2025). "The overactivation of the T/B cell was regulated by CTLA-4 and CD40 gene variants which has been confirmed in the pathogenesis of autoimmune diseases including GD." (PMID 33568133, 2021). "CD40, a key co-stimulatory molecule expressed on antigen-presenting cells, is genetically associated with a number of autoimmune diseases including Graves’ disease (GD)." (PMID 34149627, 2021). "Observations on different disease mechanisms of the BAFF pathway underlying the amalgam of autoimmune diseases are in line with the CD40 dichotomy." (PMID 34122439, 2021). "The same CD40 single nucleotide polymorphism is shared across autoimmune diseases but with opposite effects in antibody-related diseases such as SLE versus MS, where the role of shifts in B cell subsets is highlighted again." (PMID 34122439, 2021). "Previously, using FREP-MS, we identified a protein complex including eight proteins that specifically bind to the functional SNP (fSNP) rs6032664 at a CD40 locus associated with autoimmune diseases." (PMID 33371207, 2020). "The CD40 pathway has been associated with several types of autoimmune diseases including colitis, arthritis and lupus." (PMID 32155151, 2020). "Except for HLA, CTLA-4 and CD40 are apparently the most popular susceptibility genes in autoimmune diseases." (PMID 30223781, 2018). "Autoimmune diseases are typical findings in patients with combined immunodeficiency syndromes including CD40/CD40L deficiency (hyper-IgM syndromes type 3 and 1, respectively) and in predominant antibody formation disorders such as CVID." (PMID 30013564, 2018). "As a member of the TNF-receptor superfamily, the protein encoded by CD40 is associated with many diseases such as autoimmune disease, tissue inflammation, and so on." (PMID 25343742, 2014). "Recently, genome-wide association surveys have identified the association of the SNPs in CD40 locus with several autoimmune diseases including multiple sclerosis, Graves’ disease and rheumatoid arthritis." (PMID 25426283, 2014). "CD40 has been implicated in participating in many human diseases, particularly autoimmune diseases as well as the initiation and maintenance of inflammation triggered by infections through interaction with its ligand CD154." (PMID 25426283, 2014). "CD40 contributes to the susceptibility to human autoimmune diseases, in which the B and T cell pathways play key roles." (PMID 23613777, 2013). "Association with the CD40 gene region has been implicated in a number of human autoimmune diseases such as systemic lupus erythematosus (SLE), rheumatoid arthritis (RA), Crohn's disease, and Grave's disease." (PMID 23613777, 2013). "CD40 signalling has been linked to pathogenic processes of chronic inflammatory and autoimmune diseases." (PMID 23166616, 2012). "However, increased expression of CD40 ligand (CD154) leading to more CD40 activation is associated with autoimmune diseases including SLE and Sjögren’s disease, both of which also affect patients with TRAF3 haploinsufficiency (12, 36, –38)." (PMID 40773231, 2025). "CCR6, IRF5, and CD40 are all well-known autoimmune disease genes associated with RA or AS34–37." (PMID 38360850, 2024). "CD40 has been implicated in the pathogenesis of numerous autoimmune diseases." (PMID 36674855, 2023). "The CD40 gene, expressed on antigen-presenting cells, such as dendritic cells and B-cells, was shown to be a key susceptibility gene for GD, as well as other autoimmune diseases." (PMID 34149627, 2021). "Recent studies support the pathogenic role of CD40 in a number of autoimmune diseases including MS." (PMID 32111053, 2020).
autoimmune disease (continued). "In addition, antibody-mediated neutralization of peripheral macrophage CSF-1R was reported to block the development of sickness behavior measured by reduced locomotor activity and body weight loss in response to CD40 activation, a model of autoimmune disease." (PMID 32475344, 2020). "In conclusion, we have demonstrated that latent infection with γ-herpesviruses predisposes individuals to severe autoimmune disease by modulating DCs and suppressing Treg frequencies likely through DC modulation (CD40 expression) and this in turn, exaggerates CD4+ and CD8+ T cell aggression." (PMID 26356194, 2015). "The opposite genetic association of CD40 rs1883832 with increased susceptibility to MS, but with protection from RA and GD are intriguing and point to distinct roles for CD40 in the pathogenic processes in these autoimmune diseases." (PMID 26068105, 2015). "However, the molecular mechanism underlying the involvement of SNPs of CD40 gene in the autoimmune processes was unclear for MS and other autoimmune diseases." (PMID 23613777, 2013). "Our analysis suggests that the decreased CD80/CD86 ratio may be linked to the full development of the autoimmune disease, whereas the overexpression of CD40 pre-dates the occurrence of overt autoimmunity and may therefore be involved in its pathogenesis." (PMID 16507174, 2006). "We therefore propose that the decreased ratio of CD80 to CD86 in lupus DCs may be linked to the full development of the autoimmune disease, whereas the overexpression of CD40 may be important in the pathogenesis of this autoimmune disease." (PMID 16507174, 2006). "In addition, previous studies reported the association of CD40 polymorphisms with susceptibility to a number of autoimmune diseases, such as GD, multiple sclerosis, RA, Crohn disease, and with visual ischemic manifestations in individuals with biopsy-proven giant cell arteritis." (PMID 22731751, 2012). "Attempts were made to target the receptor for CD154, CD40, with anti-CD40 mAbs that have shown promise in treating autoimmune diseases, such as systemic lupus erythematous and inflammatory bowel disease." (PMID 40485581, 2025). "CD40 signaling is also essential for germinal center B cell survival, and its dysregulation results in various autoimmune diseases." (PMID 41425601, 2025). "The CD154/CD40 dyad is a key participant in the pathogenesis of many autoimmune diseases, including systemic lupus erythematosus (SLE)." (PMID 39404385, 2024). "Targeting the CD154/CD40 pathway proved its therapeutic potential in yet other autoimmune diseases, providing further support for its use in SLE patients." (PMID 39404385, 2024). "SNPS in genes: PADI4 (rs2240340), STAT4 (rs7574865), CD40 (rs4810485), PTPN22 (rs2476601), and TRAF1 (rs3761847) have been described as risk factors for the development of autoimmune diseases, including RA." (PMID 37108746, 2023). "More clinical trials are still ongoing regarding the use of monoclonal CD40 antibodies for the treatment of autoimmune diseases like Chron ́s disease or systemic lupus erythematosus." (PMID 36267276, 2022). "Another monoclonal CD40 antibody termed BI 655064 was already tested in phase 1 and 2a as a potential treatment agent for several autoimmune diseases like rheumatoid arthritis, systemic lupus erythematosus or lupus nephritis." (PMID 36267276, 2022). "Blocking the interaction between CD40/CD40L, using genetic or pharmacological (i.e., monoclonal antibody) means, has been implicated in various autoimmune diseases such as rheumatoid arthritis." (PMID 36437950, 2022). "While inhibitory CD40 targeting appears particularly attractive in the field of organ transplantation and for the treatment of autoimmune diseases, stimulatory CD40 targeting is the aim in tumor immunotherapy and vaccination against infectious pathogens." (PMID 36361658, 2022).
autoimmune disease (continued). "Inhibitory CD40 targeting appears particularly attractive in the field of organ transplantation and in the treatment of autoimmune diseases." (PMID 36361658, 2022). "Many biological agents targeting CD40 signaling have been evaluated in clinical trials for their therapeutic efficacy in patients with autoimmune diseases and have achieved partially satisfactory outcomes." (PMID 36220996, 2022). "In this study, we analyze the in vitro functional properties of KPL-404, a fully humanized IgG4 Ab anti-CD40 monoclonal antibody, which is being developed as a potential therapeutic for patients with autoimmune diseases." (PMID 33407802, 2021). "Since a suitable animal model had not been available for the translational study of the pathophysiology of SBS in autoimmune diseases, a mouse model was established by our group based on a stimulatory CD40 mAb." (PMID 34440067, 2021). "Metabolism plays important roles in regulation of other extracellular molecules currently targeted by immune therapy in autoimmune disease in autoimmunity and transplant, including CD40, CD20, CTLA-4, CD25, and CD3." (PMID 34403367, 2021). "CD40-sCD40L interaction has an emerging role in the evolution of some autoimmune diseases such as systemic lupus erythematosus, rheumatoid arthritis and mixed connective tissue disease." (PMID 31782290, 2020). "Accordingly, macrophage CD40 signaling are attributed to the pathogenesis of various human autoimmune disease and animal models of autoimmunity." (PMID 33297945, 2020). "The interaction of these genes (IL7R, CD40 and LAG3) with MHC class molecules is associated with MS and other autoimmune diseases." (PMID 32111053, 2020). "CD11b and CD40 participate in pathologic processes in various human diseases, especially inflammatory and autoimmune diseases." (PMID 32611404, 2020). "CD154 is the ligand of CD40, and this axis has been found to be of particular interest in the therapy of autoimmune diseases." (PMID 31612695, 2020). "CD40 antagonists are currently being explored for the treatment of autoimmune diseases and several anti-CD40 agonist mAbs have entered clinical development for oncological indications." (PMID 31382872, 2019). "CD40 expression on epithelium, leukocytes, and vascular endothelium is elevated in organ-specific autoimmune diseases such as Crohn’s disease, ulcerative colitis, and rheumatoid arthritis and in systemic autoimmunity such as systemic lupus erythematosus (SLE)." (PMID 31382872, 2019). "It seems likely that the finding of clustering of autoimmune diseases in individuals is contributed to by shared genetic susceptibility loci at immune regulatory genes (HLA, CTLA-4, PTPN22 and CD40)." (PMID 29529281, 2018). "Accordingly, inhibition of CD40 signaling can be beneficial in chronic inflammatory diseases including autoimmune diseases, neurodegenerative disorders, graft-versus-host disease, cancer, and atherosclerosis." (PMID 29751636, 2018). "Based on its important role in multiple physiological and pathological processes, the CD40 signaling pathway has become a vital target for treating transplantation, autoimmune diseases and cancers." (PMID 26809818, 2016). "Robust activation of B cells via BCR, CD40 or TLR9 is involved in the pathogenesis of autoimmune diseases." (PMID 26980135, 2016). "Both type I interferon (IFN-I) and CD40 play a significant role in various infectious diseases, including malaria and autoimmune disorders." (PMID 27716849, 2016). "CD40L antibodies were tested clinically for other autoimmune diseases (see “CD40 in clinical disease”)." (PMID 27146510, 2016). "T-cell CD40 seems to mediate CD8+ T-cell memory, can contribute to T-cell activation, and is associated with autoimmune disease." (PMID 27146510, 2016). "Activation and ligation of CD40 and CD40L are also associated with many neurologic and autoimmune diseases that are characterized by elevated levels of IFN-I." (PMID 27716849, 2016).
autoimmune disease (continued). "Manipulation of the CD154/CD40 interaction has been used in efforts to develop novel strategies in autoimmune diseases, results in animal models being encouraging." (PMID 25763299, 2015). "Anti-CD40 therapy has been shown to be efficacious in some autoimmune diseases, such as SLE, vasculitis, and pSS." (PMID 26339139, 2015). "Recently, increasing evidence showed that CD40 contributes to the pathogenesis of chronic inflammatory and autoimmune diseases due to its biological activity." (PMID 26474561, 2015). "Up to date, there are three proposed mechanisms for the contribution of the CD40/CD40L dyad to T lymphocyte-dependent autoimmune diseases." (PMID 26528290, 2015). "In line with its regulatory role on the adaptative immune response, the CD40/CD154 interaction contributes to autoimmune disorders in a number of animal models." (PMID 25763299, 2015). "The second proposed mechanism of CD40/CD40L contribution to autoimmune diseases occurs in secondary lymphoid organs, where T lymphocytes are primed by APCs (B lymphocytes or DCs) over-expressing CD40 either constitutively or transiently." (PMID 26528290, 2015). "A number of anti-CD40 Abs and CD40L blocking agents (anti-CD154 or CD40-Ig) are in clinical development for treatment of autoimmune diseases, transplant rejection, and cancers." (PMID 25324844, 2014). "Immunotherapies that block or stimulate the CD40 pathway hold great promise for treatment of autoimmune diseases and cancers." (PMID 25324844, 2014). "The extensive distribution and various inflammatory functions of the CD154/CD40 axis explain its involvement in the pathogenesis of many autoimmune diseases." (PMID 22110533, 2012). "CD40 is known to play a pivotal role in autoimmune disease and has gained interest as a target in transplantation and cancer therapies." (PMID 22685601, 2012). "Combining these 2 genetic alterations in CD154TGCD22−/− mice was thereby predicted to intensify CD40 signaling and autoimmune disease due to autoreactive B cell expansion and/or activation." (PMID 21799861, 2011). "The CD40 pathway is a key mediator for inflammation, and is a marker for the active stage of some autoimmune diseases." (PMID 20487533, 2010). "Using mAbs against CD40 such as the anti-human CD40 antagonist mAb, ch5D12, showed promise in autoimmune disease." (PMID 20102615, 2010). "The CD40/CD40-ligand pathway is a key component of the pathophysiology of numerous autoimmune disorders." (PMID 20634952, 2010). "A humanized anti-CD154 antibody (hu5C8) was developed with the objective of suppressing CD40-mediated immune activation in autoimmune disease and transplantation but clinical trails were complicated by increased thromboembolic events and had to be halted." (PMID 21103345, 2010). "For instance, in autoimmune diseases such as Grave's disease and Hashimoto's thyreoiditis, CD40 seems to be a marker of the active stage of the diseases." (PMID 20487533, 2010). "It is possible that a genetic deviation in a different gene leads to those conditions and that CD40 therefore by proxy is a culprit in autoimmune disease." (PMID 18446238, 2008). "Similarly, SH2B3, CD40, and CRP are linked to Sjögren’s syndrome, diabetes mellitus, and celiac disease, reinforcing the genetic connections between RA and other autoimmune diseases." (PMID 40839671, 2025). "Additionally, CD40L/CD40 antagonists show therapeutic potential for autoimmune diseases, including Sjögren’s syndrome (SjD) and systemic lupus erythematosus (SLE)." (PMID 41268556, 2025). "Furthermore, innovative therapies targeting TNFSF costimulatory pathways, such as CD40 antagonists, which have been successfully applied in autoimmune diseases, offer cross-disciplinary insights for AS treatment." (PMID 41268556, 2025).